STX11 (syntaxin 11)
Diseases named in the same sentence as STX11 in open-access papers:
STX11 is named in the same sentence as 53 diseases in open-access papers, as found by Europe PMC text mining. Sharing a sentence is not in itself a finding about the gene and the disease. The quoted sentences say what the papers report.
hemophagocytic lymphohistiocytosis (8 papers, 2014 to 2024). "Others include known genetic causes of hemophagocytic lymphohistiocytosis (HLH) such as defects in the genes PRF1, UNC13D, STX11, STXBP2, LYST, and RAB27A." (PMID 38624552, 2020).
Chediak-Higashi syndrome (5 papers, 2016 to 2025). ChC)diak-Higashi syndrome (CHS) is a rare severe genetic disorder generally characterized by partial oculocutaneous albinism (OCA), severe immunodeficiency, mild bleeding, neurological dysfunction and lymphoproliferative disorder. "Patients were divided into four groups: 1) with PRF1 mutation (n = 46), 2) with UNC13D mutation (n = 38), 3) with STX11/STXBP2 mutation (n = 25) and 4) with Griscelli syndrome type 2/ Chediak–Higashi syndrome (GS2/CHS) diagnosis (n = 44)." (PMID 40263637, 2025). "Since then, the study of familial cases allowed the recognition of genetic alterations directly affecting proteins involved in cytotoxic activity, such as Munc13-4 (FHL-3), Syntaxin 11 (FHL-4), Munc18-2 (FHL-5), RAB27A (Griscelli Syndrome type 2, GS2), LYST (Chediak-Higashi Syndrome, CHS)." (PMID 37426667, 2023). "These include familial HLH caused by autosomal recessive mutations in Perforin (PRF1), MUNC 13-4 (UNC13D), MUNC 19-2 (STXBP2), syntaxin 11 (STX11) as well as other IEIs such as Type II Hermansky-Pudlak syndrome (AP3B1), Chediak-Higashi syndrome (LYST) and Griscelli syndrome (RAB27A)." (PMID 35783679, 2022).
Familial hemophagocytic lymphohistiocytosis (5 papers, 2011 to 2024). Familial Hemophagocytic lymphohistiocytosis (FHL) is a rare primary immunodeficiency characterized by a macrophage activation syndrome (see this term) with an onset usually occurring within a few months or less common several years after birth. "Bi-allelic null mutations affecting UNC13D, STXBP2, or STX11 result in defects of lymphocyte cytotoxic degranulation and commonly cause familial hemophagocytic lymphohistiocytosis (FHL) in early life." (PMID 28848550, 2017). "For example, Stx11 (syntaxin 11) has been associated with familial hemophagocytic lymphohistiocytosis 4 in humans." (PMID 22182475, 2011). "Germline mutations in genes involved in perforin-granzyme-mediated cytotoxicity such as PRF1, UNC13D, STX11, and STXBP2 were known to cause familial hemophagocytic lymphohistiocytosis (FHL)." (PMID 38404589, 2024). "Specifically, most patients clustered within the immune dysregulation category were diagnosed with familial hemophagocytic lymphohistiocytosis (FHL) type 2 (n=3/10;30%), type 3 (n=2/10; 20%) and type 4 (n=1/10; 10%), based on homozygotic pathogenic variants in PRF1, UNC13D, and STX11, respectively." (PMID 34992599, 2021). "Germline mutations in genes involved in perforin-granzyme-mediated cytotoxicity such as PRF1, UNC13D, STX11, and STXBP2 were known to induce familial HLH (FHL)." (PMID 38404589, 2024).
Griscelli syndrome type 2 (5 papers, 2015 to 2025). Griscelli syndrome type 2 (GS2) is a rare, inherited condition that affects the skin, hair, and immune system. "The following FHL subtypes have been described: FHL-2 due to mutations in PRF1, FHL-3 (UNC13D), FHL-4 (STX11), FHL-5 (STXBP2), Griscelli Syndrome type 2 (RAB27A) and Chediack-Higashi syndrome (LYST)." (PMID 37426667, 2023). "In 13 out of the 24 (52%) a genetic diagnosis was achieved: PRF1 n = 4 (FHL2), STX11 n = 2 (FHL4), and STXBP2 n = 4 (FHL5), RAB27A n = 2 (Griscelli syndrome type 2), BIRC4 n = 1 (XIAP)." (PMID 30697212, 2018).
autoimmune disease (3 papers, 2014 to 2025). A disorder resulting from loss of function or tissue destruction of an organ or multiple organs, arising from humoral or cellular immune responses of the individual to their own tissue constituents. "While primary HLH typically manifests in children due to mutations in genes such as PRF1, UNC13D, STX11 and STXBP2, secondary HLH is more common in adults and is usually triggered by infections, cancers, autoimmune disorders or immunosuppressive therapy." (PMID 41181728, 2025).
Hemophagocytosis (3 papers, 2013 to 2023). Phagocytosis by macrophages of erythrocytes, leukocytes, platelets, and their precursors in bone marrow and other tissues. "Patients with mutated STX11 gene result in loss of immune homeostasis and severe phenotypes of hyperinflammation, such as prolonged fever, hepatosplenomegaly, and hemophagocytosis." (PMID 37165378, 2023). "Loss of syntaxin-11 function causes FHL4 in man and hemophagocytosis in mice." (PMID 24302923, 2013).
lung carcinoma (3 papers, 2023 to 2024). "The two signatures show an overlap of four genes (EMP2, AGER, STX11, GYPE) with two of them known to be linked to lung carcinoma." (PMID 38993634, 2024). "However, high expression of ADAMTS8, CD36, DPYSL2, PLEKHH2, STX11, and TCF21 tends to lead to better prognosis, which coincides with the difference in expression of these HUB genes in normal samples and lung cancer samples." (PMID 37409245, 2023).
peripheral T-cell lymphomas (3 papers, 2020 to 2024). "Furthermore, STX11 has emerged as a novel tumor suppressor gene implicated in peripheral T-cell lymphoma." (PMID 37715537, 2024). "It has previously been reported that STX11 functions as a tumor suppressor gene in peripheral T-cell lymphomas." (PMID 32915772, 2020). "However, STX11 was found downregulated in HCC tissues, and it has been reported to function as a tumor suppressor gene in peripheral T-cell lymphomas." (PMID 35707353, 2022).
viral infection (3 papers, 2014 to 2024). "The 7 patients with STX11 mutations also had viral infection that seemed to trigger HLH disease onset." (PMID 25233452, 2014).
primary immunodeficiencies (2 papers, 2015 to 2018). "The Sec/Munc protein, Munc18‐2, and its binding partner Syntaxin 11 (STX11) are both required for granule secretion, with mutations in either leading to the primary immunodeficiency, Familial Haemophagocytic Lymphohistiocytosis (FHL4 and 5)." (PMID 26771955, 2015). "Furthermore, several heterozygous variants were identified in genes associated with known primary immunodeficiencies that are inherited in an autosomal recessive manner, such as LYST, LRBA, RAG1, EXTL3, and STX11 (Group 4)." (PMID 30723478, 2018).
acute myeloid leukemia (1 paper, 2015). Acute myeloid leukemia (AML) is a group of neoplasms arising from precursor cells committed to the myeloid cell-line differentiation. "Furthermore, defects in the gene encoding for the syntaxin-11 protein have been shown to cause both HLH and acute myeloid leukemia (AML)." (PMID 26467435, 2015).
Aleutian disease (1 paper, 2024). "From this, we identified several candidate genes contributing to the growth and feed efficiency (ARID1B, APPL1, TOX, and GPC5), reproduction (GRM1, RNASE10, WNT3, WNT3A, and WNT9B), pelt quality (MYO10, and LIMS1), and Aleutian disease tests (IFNGR2, APEX1, UBE3A, and STX11)." (PMID 38167844, 2024).
antibody deficiency (1 paper, 2025). "While the mechanism underlying antibody deficiency in UNC13D deficiency remains unclear, insights can be gleaned from mutations in other vesicle transport-related genes, such as STX11." (PMID 40901478, 2025).
colorectal cancer (1 paper, 2025). A primary or metastatic malignant neoplasm that affects the colon or rectum. "In previous studies, the relationships between STX11 and both lung adenocarcinoma and colorectal cancer have been reported, but the relationships are still unclear." (PMID 40898016, 2025).
COVID-19 (1 paper, 2023). A disease caused by infection with severe acute respiratory syndrome coronavirus 2. "Collectively, these results suggest that DDIT3, MAFF, and PNRC1 play important roles in OA and COVID-19 pathogenesis, while STX11 lacks specificity." (PMID 37283761, 2023).
HIV-1 infection (1 paper, 2023). The type species of lentivirus and the etiologic agent of acquired immunodeficiency syndrome (AIDS). "Genome-wide association studies in humans have shown that the UTRN and STX11 genes are associated with lung function and pre-treatment viral load in HIV-1 infection, respectively." (PMID 37710159, 2023).
lung fibrosis (1 paper, 2024). "After AAV-STX11 instillation, STX11 expression was obviously elevated, which accompanied with decrease of lung fibrosis." (PMID 39523374, 2024). "In order to explore the expression of STX11 in lung fibrosis, we screened the database related to IPF in GEO database." (PMID 39523374, 2024). "To explore the role of STX11 in BLM-induced lung fibrosis, we intratracheally instilled AAV-STX11 into the mice lung." (PMID 39523374, 2024). "Altogether, these results demonstrated reduced expression of STX11 in lung fibrosis, suggesting its possible involvement in the progression of lung fibrosis." (PMID 39523374, 2024). "In vivo, overexpression of STX11 exerted its protective role in the mice with BLM-induced lung fibrosis." (PMID 39523374, 2024). "We also investigated whether overexpression of STX11 alleviated BLM-induced pulmonary fibrosis in mice." (PMID 39523374, 2024). "First, we found that STX11 was markedly downregulated in the lung tissues from IPF patients (GEO database and clinical samples) as well as mice with BLM-induced lung fibrosis." (PMID 39523374, 2024). "Then, overexpression of STX11 inhibited HLF activation via promoting HLF autophagy and reduced the severity of BLM-induced pulmonary fibrosis in mice." (PMID 39523374, 2024). "In the current study, we examined the expression of STX11 and SNAP25 in the lung tissues from IPF patients and mice with BLM-induced pulmonary fibrosis as well as in the activated fibroblasts." (PMID 39523374, 2024). "Here, we showed that the expression levels of STX11 and SNAP25 were downregulated in the lung tissues from patients with IPF and mice with bleomycin (BLM)-induced lung fibrosis as well as in the activated fibroblasts." (PMID 39523374, 2024).
lymphoma (1 paper, 2024). A malignant (clonal) proliferation of B- lymphocytes or T- lymphocytes which involves the lymph nodes, bone marrow and/or extranodal sites. "In this study, we reported a unique group of 3 patients with germline mutations of UNC13D and STX11 genes and presented as adult-onset peripheral T-cell lymphoma (PTCL) with cytotoxic T-cell phenotype and atypical lymphoma presentations." (PMID 38404589, 2024).
osteoarthritis (1 paper, 2025). A noninflammatory degenerative joint disease occurring chiefly in older persons, characterized by degeneration of the articular cartilage, hypertrophy of bone at the margins and changes in the synovial membrane. "In a bioinformatics study of rheumatoid arthritis and osteoarthritis, STX11 was found to be highly enriched in protein–protein interaction networks." (PMID 40809843, 2025). "Moreover, the correlation analysis of SLC38A1 and STX11 with all immune cells showed a negative correlation with NK cells, further suggesting that SLC38A1 and STX11 may influence the development of osteoarthritis through the immune infiltration of NK cells." (PMID 40809843, 2025).
Sepsis (1 paper, 2025). Sepsis is defined as life-threatening organ dysfunction caused by a dysregulated host response to infection. "HLH is a hyperinflammatory syndrome in which familial (primary) forms arise from biallelic variants in cytotoxic-pathway genes (e.g., PRF1, UNC13D, STX11, STXBP2), and in neonates the presentation may closely mimic sepsis." (PMID 41477640, 2025).
T-cell lymphomas (1 paper, 2025). "However, only a few studies have focused on the role of STX11 in solid tumors, and it has been identified as a tumor suppressor in T-cell lymphomas; yet, the mechanism is still unclear." (PMID 40898016, 2025).
tumor (9 papers, 2016 to 2026). "Although we confirmed that the HPV-associated gene STX11 can play an anticancer role by regulating the polarization of tumor-associated macrophages, there are still shortcomings in this study." (PMID 40898016, 2025). "The expression patterns and clinical significance of STX11 were determined through bioinformatics analysis, and its effects on modulating tumor-associated macrophages (TAMs) were confirmed by real-time qPCR and Western blotting." (PMID 40898016, 2025). "We further investigated the effect of STX11 on repolarized tumor-associated macrophages (TAMs)." (PMID 40898016, 2025). "By overexpressing syntaxin 11 in autologous tumour cells obtained from surgical resections, we generated MHC Ihigh/CD80high/CD86high dendritic-cell-like cells." (PMID 41612046, 2026). "Consistent with the results from the BC datasets, the results of single-cell RNA sequencing revealed that STX11 was expressed mainly in macrophages in a variety of tumors but was rarely expressed in tumor cells." (PMID 40898016, 2025). "The patients with BC with high STX11 expression presented higher immune and stromal scores and lower tumor purity." (PMID 40898016, 2025). "CD24, CD74, PGK1 showed significantly higher expression in tumour tissue compared with tumour adjacent normal tissue, while STX11 and NFKBIA showed the opposite trend (p < .001 for all)." (PMID 34187256, 2021). "In contrast, the decreased expression of Tcp11, a determinant of sperm morphology, as well as the decreased expression of Stx11, a gene involved in tumor suppression, suggest roles for these factors in the small eye phenotype of the Cryaa-R49C-homo lenses." (PMID 29338044, 2018). "In addition to the TCGA cohort, we confirmed that STX11 expression was downregulated in tumor tissues in the GSE42568 and GSE70947 cohorts." (PMID 40898016, 2025). "Moreover, we demonstrated that STX11 promoted the polarization of antitumor M1-like macrophages in BC and that macrophages overexpressing STX11 inhibited tumor progression by regulating the PI3K–AKT signaling pathway." (PMID 40898016, 2025). "We confirmed that STX11-overexpressing macrophages can inhibit the malignancy of BC cells by coculture, suggesting that these cells secrete active substances to regulate the fate of tumor cells." (PMID 40898016, 2025). "In addition, STX11 was demonstrated to be a tumor suppressor that inhibits the PI3K–AKT signaling pathway in BC cells to determine malignancy by regulating macrophage polarization." (PMID 40898016, 2025). "In orthotopic BC models, macrophages overexpressing STX11 significantly suppressed tumor growth." (PMID 40898016, 2025). "Thus, we further analyzed the relationship between the tumor microenvironment and STX11 expression." (PMID 40898016, 2025). "Among these genes, EFNA4 and TEDC2 were significantly upregulated, whereas CDC42EP2, STX11, THBD, TMEM88, and GPM6A were notably downregulated in tumor tissues compared with adjacent normal tissues." (PMID 42196266, 2026). "Here we identify syntaxin 11 as a key regulator that enhances the expression of MHC I and co-stimulatory molecules CD80/CD86 on tumour cell membranes, enabling cancer cells to acquire dendritic-cell-like features." (PMID 41612046, 2026). "The tumor volumes in the MCF-7 and MCF-7 + macrophage groups were significantly greater than that in the MCF7 + macrophage (STX11-overexpressing) group, and the weight of the tumors in this group was also the lowest." (PMID 40898016, 2025).
cancer (5 papers, 2017 to 2026). A tumor composed of atypical neoplastic, often pleomorphic cells that invade other tissues. "In the Cancer Genome Atlas (TCGA) test dataset, eight genes were detected, and six of them were survival associated (DPP4, FFAR4, RASA3, RASGRF1, XCR1, and STX11)." (PMID 34760708, 2021). "With this procedure, we recorded about 100 STED platelet images each, for six different proteins (VAMP7, VAMP8, STX11, SNAP23, TSP1, and VEGF) and for five different categories of platelets; incubated with cancer cells (MCF-7, MDA-MD-231, EFO-21), non-cancer cells (MCF-10A), or no cells at all (R)." (PMID 35729633, 2022).
immune disease (3 papers, 2014 to 2025). "Mutations in STX11 are associated with impaired exocytosis of lytic granules and predispose humans to an immune disorder called familial hemophagocytic lymphohistiocytosis subtype 4 (FHL-4)." (PMID 36728431, 2023). "STX11 is highly expressed in cells of the immune system and interestingly has an already established role in immune disease." (PMID 25674084, 2014).
infection (3 papers, 2020 to 2023). The state of being infected such as from the introduction of a foreign agent such as serum, vaccine, antigenic substance or organism. "Therefore, using CRISPR/Cas9 gene editing, we generated STX4- and STX11-deficient cells and examined the export of typhoid toxin in the resulting cells after infection with S. Typhi." (PMID 35579416, 2022). "The difference in C. burnetii replication in STX11-deficient cells was observed at roughly 3 to 5 days postinfection (dpi), which indicates that STX11 function interferes with C. burnetii replication at a later stage of infection." (PMID 36728431, 2023). "Because macrophages are the primary cells that support C. burnetii replication during human infection, the role of STX11 in cell autonomous defense was investigated using the human monocytic cell line THP-1." (PMID 36728431, 2023).
bacterial infection (2 papers, 2016 to 2023). "Findings presented here support a nonlymphocyte role for STX11 in controlling intracellular bacterial infection." (PMID 36728431, 2023).
STX11 also shares sentences with these, for which no sentence is quoted: macrophage activation syndrome (2 papers); Pancytopenia (2); acquired immunodeficiencies (1); Arthritis (1); autism (1); breast carcinoma (1); CACP) syndrome (1); dwarfism (1); endothelial dysfunction (1); Griscelli syndrome (1); hematological malignancies (1); Hepatosplenomegaly (1); hypertriglyceridemia (1); Hypofibrinogenemia (1); Immunodeficiency (1); lung adenocarcinoma (1); Lymphadenopathy (1); Majeed syndrome (1); muscular dystrophy (1); myelodysplastic syndrome (1); partial albinism (1); prostate carcinoma (1); psychiatric disorder (1); rheumatoid arthritis (1); schizophrenia (1); Splenomegaly (1); systemic lupus erythematosus (1).